OTUD7B (OTU deubiquitinase 7B)
Diseases named in the same sentence as OTUD7B in open-access papers (continued):
Sharing a sentence is not in itself a finding about the gene and the disease.
lung carcinoma (8 papers, 2019 to 2025). "Accumulated evidence indicated that low expression of OTUD7B associated with inferior survival in various solid tumors, such as breast cancer, hepatocellular carcinoma, and lung cancer 6-8." (PMID 35154465, 2022). "Lung cancer patients carry many gene mutations, including mutations in OTUD7B." (PMID 33198776, 2020). "Moreover, we found that OTUD7B regulation in lung cancer progression associates with tumor angiogenesis via Akt/VEGF pathway." (PMID 31572671, 2019). "OTUD7B facilitates lung cancer cell metastasis via the Akt/vascular endothelial growth factor signaling pathway." (PMID 40746896, 2025). "Eliminating OTUD7B significantly reduced the incidence of spontaneous lung cancer in mice, and elevated OTUD7B expression in lung adenocarcinoma tissues has been positively correlated with poor lung cancer prognosis." (PMID 40746896, 2025). "In lung cancer, OTUD7B facilitated osimertinib resistance in lung adenocarcinoma cells through PIK3C3 stabilization and PIK3C2A transcription." (PMID 40469292, 2025). "In lung cancer, OTUD7B displays multifaceted roles in lung cancer pathogenesis with divergent clinical implications." (PMID 40469292, 2025). "First, we assessed the protein expression of OTUD7B protein in several lung cancer cells and found that it was lowest in H1299 cells." (PMID 33198776, 2020). "To confirm that OTUD7B inhibits LCL161-induced lung cancer cell metastasis in vivo, we stably transfected empty vector, HA-OTUD7B(WT) and HA-OTUD7B(CH) plasmids into H1299 cells and implanted the cells into nude mice via caudal vein injection." (PMID 33198776, 2020). "The aim of this study was to evaluate the prognostic significance of OTUD7B in patients with lung adenocarcinoma and squamous carcinoma and to characterize its molecular mechanisms in lung cancer progression and metastasis." (PMID 31572671, 2019). "To investigate the potential clinical relevance of OTUD7B in lung cancer, we assessed lung cancer tissue samples and matched adjacent normal lung tissue samples from 214 human subjects (143 LUSC cases and 71 LAD cases)." (PMID 31572671, 2019). "High expression of OTUD7B predicts metastasis and poor survival in NSCLC patients, which suggested potential role of OTUD7B in lung cancer initiation and progression." (PMID 31572671, 2019). "Next, we divided the samples into groups based on metastasis and the AJCC stage to study the correlation of OTUD7B expression with lung cancer development." (PMID 31572671, 2019). "Furthermore, OTUD7B can inhibit LCL161-induced lung cancer cell invasion and migration by deubiquitinating TRAF3, inhibiting NIK and preventing non-canonical NF-κB activation." (PMID 33198776, 2020). "OTUD7B promotes lung cancer cell proliferation and migration via Akt/VEGF signal pathway." (PMID 31572671, 2019). "In addition, OTUD7B was demonstrated to promote tumor growth in NCI-H358 lung cancer xenografts." (PMID 31572671, 2019). "In brief, OTUD7B deubiquitinates TRAF3 and inhibits NIK to suppress LCL161-induced lung cancer cell invasion and migration." (PMID 33198776, 2020). "A recent study showed that OTUD7B regulated invasion and migration via AKT pathway in lung cancer cells." (PMID 33198776, 2020). "Expression levels of OTUD7B, NIK and TRAF3 in tissue samples from lung cancer patients were examined by immunohistochemistry." (PMID 33198776, 2020). "Our study highlights the importance of OTUD7B in the suppression of LCL161-induced lung cancer cell invasion and migration, and the results are meaningful for selecting lung cancer patients suitable for LCL161 treatment." (PMID 33198776, 2020). "To verify the clinical application value of our results, we analysed the expression of OTUD7B, TRAF3 and NIK in 146 lung cancer tissues and their correlation with prognosis." (PMID 33198776, 2020).
lung carcinoma (continued). "MTT proliferation, colony formation, migration and invasion assays and immunoblotting assay in NCI-H358 and A549 cell lines suggested that OTUD7B enhances EGF-induced Akt signal transduction and promotes lung cancer cell proliferation and migration." (PMID 31572671, 2019). "For instance, OTUD7B functions to prevent TRAF3 degradation in lung cancer cell cells, suppressing their invasiveness though the non-canonical NF-κB pathway." (PMID 39990225, 2025). "We found that high expression of OTUD7B was more frequently observed in early-stage lung cancer patients without lymph node metastasis." (PMID 33198776, 2020). "Taken together, these data shows that LCL161 can induce lung cancer cell intrapulmonary metastasis in vivo and that metastasis is inhibited by OTUD7B but not by mutant OTUD7B, which lacks DUB activity." (PMID 33198776, 2020). "OTUD7B, also called Cezanne, was identified as an essential regulator of the NF-κB pathway and cancer proliferation, although its physiological function in lung cancer has not been well-defined." (PMID 31572671, 2019). "However, whether OTUD7B can inhibit LCL161-induced invasion and migration and be used to select a target population in LCL161 treatment for lung cancer is unclear." (PMID 33198776, 2020). "In our study, we found that overexpressed OTUD7B inhibits NIK and the non-canonical NF-κB pathway in lung cancer cells by binding to and deubiquitinating TRAF3." (PMID 33198776, 2020). "Consistently, OTUD7B (WT) but not OTUD7B (CH) inhibited activation of the non-canonical NF-κB pathway and LCL161-induced lung cancer cell invasion and migration." (PMID 33198776, 2020).
pancreatic cancer (6 papers, 2019 to 2025). "Dysregulation of OTUD7B has been observed in several types of cancer, such as lung, breast, liver, and pancreatic cancers." (PMID 37371581, 2023). "Moreover, a lncRNA-miRNA-mRNA axis promoting tumor progression and involving OTUD7B has been reported in pancreatic cancer." (PMID 33371395, 2020). "Furthermore, RHBDL2 plays a crucial role in pancreatic cancer, where it enhances proliferation, migration, and invasion by stabilizing N1ICD through interactions with OTUD7B and activation of the Notch signalling pathway." (PMID 40668798, 2025).
hepatocellular carcinoma (5 papers, 2019 to 2025). A malignant tumor that arises from hepatocytes. "To first verify the expression status of OTUD7B in hepatocellular carcinoma, we performed immunohistochemical (IHC) staining against a commercial tissue microarray containing 15 pairs of liver cancer and normal adjacent tissues." (PMID 39990225, 2025). "Research has repeatedly shown that OTUD7B is overexpressed and hold the vital role in in various types of cancers progress including hepatocellular carcinoma lung adenocarcinoma, Breast, squamous cell carcinoma." (PMID 31747939, 2019). "This study investigates the role of the deubiquitinase enzyme OTUD7B in hepatocellular carcinoma (HCC), where it is notably downregulated and proposed to function as a tumor suppressor." (PMID 39990225, 2025). "OTUD7B not only responds to the immune system but also functions as an oncogene; OTUD7B induces lung squamous carcinoma via the AKT/VEGF signaling pathway and activates the NF-κB signaling pathway to increase resistance to apoptosis in hepatocellular carcinoma." (PMID 34201062, 2021).
lung adenocarcinoma (5 papers, 2018 to 2025). A carcinoma that arises from the lung and is characterized by the presence of malignant glandular epithelial cells. "Recent studies have demonstrated OTUD7B as a gene highly expressed in lung adenocarcinoma tissues." (PMID 31572671, 2019). "Although the effects of COPS5 knock-down in SNAIL expression was most predominant amongst the candidates in lung adenocarcinomas, the other four DUBs (JOSD1, OTUB1, OTUD7A, and OTUD7B) could potentially regulate SNAIL expression in other cancer such as cervical cancers." (PMID 29755680, 2018).
ovarian tumor (5 papers, 2020 to 2025). "This gene encodes OTU domain-containing protein 7B (OTUD7B), which is a deubiquitylase belonging to the A20 subgroup of ovarian tumor (OTU) protein superfamily." (PMID 40557284, 2025). "Cellular zinc finger anti-NF-kappa-B protein (Cezanne, also called OTU domain-containing protein 7B, OTUD7B) is a member of the ovarian tumor protease (OTU)-deubiquitinating family." (PMID 37596251, 2023). "Thus, Pearson correlation analysis between the expression level of B4GALT5 and OTU (ovarian tumour) family deubiquitinases (OTUB1, OTUB2, OTUD1, YOD1, OTUD3, OTUD4, OTUD7B) was performed." (PMID 36611197, 2023). "Another DUB, OTUD7B, has a sequence homologous to A20 called the ovarian tumour (OTU) domain and is involved in the regulation of the non-canonical NF-κB pathway." (PMID 33198776, 2020).
liver cancer (3 papers, 2019 to 2025). An epithelial or non-epithelial malignant neoplasm that arises from the liver. "Similar to tissues, the protein and mRNA levels of OTUD7B in three liver cancer cell lines (HepG2, SMMC-7721 and SK-Hep-1) were reduced relative to the normal liver cell line THLE-2." (PMID 39990225, 2025). "In this report, we sought to better understand the contribution of OTUD7B to liver cancer tumorigenesis." (PMID 39990225, 2025). "Together these findings propose OTUD7B as a potential therapeutic target for liver cancer." (PMID 39990225, 2025). "A previous study showed that OTUD7B can inhibit the NF-κB pathway in liver cancer." (PMID 33198776, 2020). "Thus, OTUD7B plays a definitive role in promoting apoptosis in liver cancer cells." (PMID 39990225, 2025). "Here using several methodical approaches, we confirmed the differential reduction of OTUD7B in HCC compared to normal liver tissue, reinforcing its unique role in the context of liver cancer." (PMID 39990225, 2025).
breast tumor (2 papers, 2018 to 2025). "High expression of OTU deubiquitinase 7B (OTUD7B) and LSD1 is associated with higher breast tumor grades." (PMID 40479062, 2025). "Similarly, among patients receiving post-operative paclitaxel-based chemotherapy, our results showed that OTUD7B mRNA levels in breast tumors derived from patients with non-pCR were predominantly elevated compared to those of patients with pCR." (PMID 29416635, 2018).
cardiac hypertrophy (2 papers, 2025 to 2026). "OTUD7B deficiency worsens pathological cardiac hypertrophy and dysfunction, whereas its overexpression mitigates hypertrophy." (PMID 40158182, 2025). "The potential molecular mechanisms underlying OTUD7B's regulation of cardiac hypertrophy were explored through transcriptome analysis and further validated in cardiomyocytes." (PMID 40158182, 2025). "This study examined the function of a DUB, ovarian tumor domain-containing 7B (OTUD7B), in cardiac hypertrophy." (PMID 41695487, 2026). "Here, we investigated the role and regulating mechanism of ovarian tumor domain-containing 7B (OTUD7B) in cardiac hypertrophy by modulating fatty acid metabolism." (PMID 40158182, 2025). "This study is the first to demonstrate that OTUD7B mitigates pathological cardiac hypertrophy by stabilizing HNF4α through deubiquitination." (PMID 40158182, 2025). "Given the critical role of these processes in cardiac hypertrophy, it is essential to investigate the impact of OTUD7B on fatty acid metabolism and regulated cell death." (PMID 40158182, 2025). "Mice subjected to transverse aortic constriction (TAC) and cardiomyocytes treated with phenylephrine (PE) were used to explore the role of OTUD7B in myocardial hypertrophy." (PMID 40158182, 2025). "Collectively, these findings demonstrate that OTUD7B knockdown exacerbates pressure overload-induced myocardial hypertrophy and fibrosis, leading to deteriorated cardiac function." (PMID 40158182, 2025). "In summary, our findings identify OTUD7B as a potential candidate for treating cardiac hypertrophy and highlight the promise of modulating FAO via an HNF4α-targeted strategy." (PMID 40158182, 2025). "Given that OTUD7B knockdown exacerbates cardiac hypertrophy and its expression is reduced in myocardial tissue under TAC conditions, we subsequently explored the role of OTUD7B in modulating cardiac hypertrophy by influencing cardiomyocyte function iv vitro." (PMID 40158182, 2025). "Mechanistically, transcriptomic analysis identified OTUD7B plays a role in the regulation of fatty acid metabolism and pathological cardiac hypertrophy." (PMID 40158182, 2025). "Histological examinations using H&E, WGA, Masson, and Sirius Red staining consistently indicated that OTUD7B knockdown significantly intensified pressure overload-induced cardiac hypertrophy and fibrosis." (PMID 40158182, 2025). "Together, these findings indicate that Fer-1 treatment effectively mitigated ferroptosis, myocardial hypertrophy, and fibrosis resulting from OTUD7B knockdown." (PMID 40158182, 2025). "Moreover, cardiomyocyte-specific OTUD7B overexpression exacerbated TAC-induced cardiac hypertrophy and dysfunction by deubiquitinating SERCA2a at K628." (PMID 41695487, 2026). "Finally, ferroptosis inhibitors, ferrostatin-1, alleviated OTUD7B inhibition-induced ferroptosis, fatty acid metabolism suppression, and myocardial hypertrophy." (PMID 40158182, 2025). "We confirmed that OTUD7B is involved in the regulation of ferroptosis in pressure overload-induced cardiac hypertrophy and highlighted that OTUD7B alleviates cardiac hypertrophy by regulating ferroptosis and fatty acid oxidation through deubiquitination and stabilization of HNF4α." (PMID 40158182, 2025). "Both their study and ours establish OTUD7B as a protective factor in cardiac hypertrophy." (PMID 40158182, 2025). "Similarly, analysis of the GSE221396 dataset, comprising three control and three Ang II-induced cardiac hypertrophy mice, revealed downregulation of OTUD7B." (PMID 40158182, 2025). "Cardiomyocyte-specific deletion of OTUD7B significantly mitigated angiotensin II (Ang II)- and transverse aortic constriction (TAC)-induced cardiac hypertrophy and dysfunction in mice." (PMID 41695487, 2026). "In the human cardiac hypertrophy dataset, GSE89714, OTUD7B and ZRANB1 was identified as the downregulated members of the OTU family." (PMID 40158182, 2025).
cardiac hypertrophy (continued). "In conclusion, this study provides robust evidence that OTUD7B-mediated deubiquitination of HNF4α is pivotal in reprogramming FAO and regulating ferroptosis during pressure overload-induced cardiac hypertrophy." (PMID 40158182, 2025). "For OTUD7B, mRNA expression levels showed significant differences between PBS and PE or Ang II treatment, WB analysis further confirmed a notable reduction in OTUD7B protein levels in the myocardial hypertrophy models." (PMID 40158182, 2025).
cervical cancer (2 papers, 2018 to 2025). A primary or metastatic malignant neoplasm involving the cervix.
diffuse large B-cell lymphoma (2 papers, 2022 to 2023). "OTUD7B is a prognostic maker in diffuse large B-cell lymphoma and NSCLC, as well as a potential therapeutic target for myocardial infarction by ameliorating fibrosis, and predicts poor responses to paclitaxel in TNBC." (PMID 36672466, 2023). "In addition to NSCLC, overexpression of OTUD7B was also observed in diffuse large B-cell lymphoma and served as a prognostic marker." (PMID 36672466, 2023). "Our data illustrated that OTUD7B deficiency is a negative predictor of clinical outcome, and might be a potential therapeutic target in the treatment of diffuse large B-cell lymphoma." (PMID 35154465, 2022). "We detected OTUD7B expression levels in 160 diffuse large B-cell lymphoma (DLBCL) tissue samples by immunohistochemistry, and analyzed correlations between its expression and clinic-pathologic parameters as well as clinical outcomes." (PMID 35154465, 2022).
gastric cancer (2 papers, 2015 to 2025). A primary or metastatic malignant neoplasm involving the stomach. "OTUD7B overexpression has been linked to increased gastric cancer cell proliferation and metastasis both in experimental setups and in live subjects, while the suppression of OTUD7B has yielded contrary biological effects." (PMID 39936032, 2025). "Through its actions, OTUD7B promotes the progression of gastric cancer by enhancing the activity of the YAP1/NUAK2 axis." (PMID 39936032, 2025). "Herein, analysis by publicly available algorithms and our serial experimental results demonstrate that CYLD, TAX1BP1, and OTUD7B are bona fide targets of miR-500 in gastric cancer." (PMID 25595906, 2015). "Taken together, our results suggest that miR-500 overexpression activates the NF-κB signalling pathway by repressing CYLD, TAX1BP1, and OTUD7B, and consequently results in gastric cancer aggressiveness and poor clinical outcomes." (PMID 25595906, 2015). "Lastly, we examined whether miR-500–mediated suppression of CYLD, TAX1BP1, and OTUD7B, and NF-κB activity in gastric cancers are clinically relevant." (PMID 25595906, 2015). "Therefore, our results suggest a novel mechanism of DUB dysregulation involving CYLD, A20, and OTUD7B in gastric cancer and provide a functionally and clinically relevant epigenetic mechanism in cancer progression." (PMID 25595906, 2015).
acute promyelocytic leukemia (1 paper, 2023). An aggressive form of acute myeloid leukemia (AML), characterized by arrest of leukocyte differentiation at the promyelocyte stage, due to a specific chromosomal translocation t(15;17) in myeloid cells. "We firstly depleted OTUD7B in THP1 (monocytes), HL-60 (acute promyelocytic leukemia) and K562 (chronic myelogenous leukemia) cells and found OTUD7B knockdown led to reduced Akt-pS473 signals." (PMID 36672466, 2023).
adenoma (1 paper, 2016). A neoplasm arising from the epithelium. "Truncating mutations were also validated in SCUBE2, RELN, FBXW7, MLL3, WTX/FAM123B, OTUD7B and KPRP across the MAP and FAP adenomas." (PMID 26414517, 2016).
B-cell lymphoma (1 paper, 2022). "Functional studies showed that forced expression of OTUD7B sensitized B-cell lymphoma cell lines to doxorubicin." (PMID 35154465, 2022). "The results showed that Chidamide remarkably up-regulated OTUD7B expression levels in several B-cell lymphoma cell lines." (PMID 35154465, 2022).
cerebral malaria (1 paper, 2023). A sequestration of Plasmodium falciparum in the brain, which can cause coma and/or seizures. "We show that mice with DC-specific OTUD7b-deficiency displayed DC apoptosis and a failure to induce CD8+ T cell-mediated brain pathology, experimental cerebral malaria, in a murine malaria infection model." (PMID 37516734, 2023).
esophageal squamous cell carcinoma (1 paper, 2025). Esophageal squamous cell carcinoma (ESCC) is a type of esophageal carcinoma (EC) that can affect any part of the esophagus, but is usually located in the upper or middle third. "This study explored the role of ovarian tumor deubiquitinase 7B (OTUD7B) in esophageal squamous cell carcinoma (ESCC) in the context of m6A methylation and the hypoxia-inducible factor-1α (HIF-1α) pathway." (PMID 40746896, 2025).